FAM3A (FAM3 metabolism regulating signaling molecule A)
Description:
May act as a defensin against invading fungal microorganisms.
Synonyms: 2-19; 2.19; DXS560S; XAP-7; DLD
Tractability: Antibody: UniProt places it where antibodies can reach, with high confidence; UniProt predicts a signal peptide or a membrane-spanning region; its Gene Ontology location is reachable by antibodies, with medium confidence. PROTAC: ubiquitination databases record sites on it; its protein half-life has been measured.
Gene: Protein-coding gene on chromosome X (154,506,159 to 154,516,882, reverse strand). Ensembl gene ENSG00000071889.
Subcellular location: Secreted
Subcellular location (Human Protein Atlas): Nucleoli rim; Mitotic chromosome; Nucleoplasm; Predicted to be secreted
Gene Ontology:
Molecular function: cytokine activity
Biological process: antifungal humoral response; antimicrobial humoral immune response mediated by antimicrobial peptide; negative regulation of antifungal innate immune response; signal transduction
Cellular component: extracellular region
Homologues: Orthologues: rabbit FAM3A (95% identical), guinea pig FAM3A (94% identical), pig FAM3A (93% identical), mouse Fam3a (91% identical), rat Fam3a (91% identical), chimpanzee FAM3A (86% identical), macaque FAM3A (85% identical), tropical clawed frog fam3a (68% identical), zebrafish fam3a (67% identical), dog FAM3A (53% identical), Caenorhabditis elegans famp-1 (32% identical). Paralogues in human: FAM3D (53% identical), FAM3C (49% identical), FAM3B (33% identical).
Diseases named in the same sentence as FAM3A in open-access papers:
FAM3A is named in the same sentence as 25 diseases in open-access papers, as found by Europe PMC text mining. Sharing a sentence is not in itself a finding about the gene and the disease. The quoted sentences say what the papers report.
Hyperglycemia (6 papers, 2017 to 2025). An increased concentration of glucose in the blood. "Notably, doxepin’s beneficial effects on hyperglycemia, fatty liver and obesity were completely abolished in FAM3A-deficient mice." (PMID 35800345, 2022). "Activation of FAM3A by doxepin or imipramine treatment markedly ameliorated hyperglycemia, liver steatosis, and obesity in obese mice." (PMID 38937853, 2024). "Overexpression of FAM3A has been evidenced to reduce hyperglycemia via the PI3K/Akt signaling pathway and protect mitochondrial function in neuronal HT22 cells." (PMID 34853925, 2023). "As a target of peroxisome proliferator-activated receptor γ (PPAR γ), FAM3A has been shown to inhibit hyperglycemia and insulin resistance via the PI3K/AKT signaling pathway." (PMID 34853925, 2023). "Hepatic activation of FAM3A markedly attenuated hyperglycemia, insulin resistance and fatty liver in obese diabetic mice via the activation of Akt signaling pathway." (PMID 28515350, 2017). "Only a recent study showed that antidepressants such as diphenylpyraline could activate FAM3A to suppress hepatic gluconeogenesis and lipogenesis, finally improving hyperglycemia and steatosis in obese diabetic mice." (PMID 37051599, 2023). "Hepatic miR-423-5p overexpression inhibits FAM3A-ATP-P2R signaling pathway to promote hyperglycemia, insulin resistance and steatosis in normal mice, while miR-423-5p inhibition activated FAM3A-ATP-P2R signaling pathway to ameliorate hyperglycemia and fatty liver in obese mice." (PMID 35800345, 2022). "Furthermore, we found that antidepressive drug doxepin can activate FAM3A-ATP signaling pathway to ameliorate hyperglycemia and fatty liver in HFD mice and db/db mice." (PMID 35800345, 2022). "Notably, long-term hepatic FAM3A overexpression failed to improve the impaired glucose tolerance and elevated fasting hyperglycemia in PANX1-deficient mice." (PMID 38937853, 2024). "Rosiglitazone administration upregulated FAM3A expression in HFD-fed diabetic mouse tissues with improved adipokine profile and hyperglycemia." (PMID 28515350, 2017). "Moreover, it has been reported that activation of FAM3A-ATP-P2R pathway due to the inhibition of NFE2/miR-423-5p axis in the liver is involved in exercise-induced improvement of insulin resistance and hyperglycemia in diabetic animals." (PMID 35800345, 2022).
Insulin resistance (4 papers, 2022 to 2025). Increased resistance towards insulin, that is, diminished effectiveness of insulin in reducing blood glucose levels. "In the present study, the functions of FAM3A in uncoupling lipid accumulation in muscles and insulin resistance (IR) were addressed." (PMID 41353211, 2025). "Previous research has predominantly focused on the role of FAM3A in insulin resistance, gluconeogenesis, lipogenesis, hypertension, chondrocyte apoptosis, and cardiovascular hypertrophy." (PMID 34853925, 2023). "Taken together, these findings suggest that FAM3A may promote lipid accumulation in muscle and ameliorate insulin resistance and inflammation by enhancing PPARα signaling." (PMID 41353211, 2025). "In addition to these findings concerning inflammation and insulin resistance, the effects of FAM3A on mitochondrial homeostasis were explored in our study because of the significance of mitochondria in bioenergetic efficiency and metabolism." (PMID 41353211, 2025).
diabetes (3 papers, 2022 to 2025). "Previous studies have indicated a role of FAM3A in IR and diabetes." (PMID 41353211, 2025). "Given the crucial roles played by repressed ATP synthesis and release in the pathogenesis of diabetes and NAFLD, our findings reveal that targeting FAM3A represents an attractive strategy for combating metabolic disorders." (PMID 38937853, 2024). "By measuring the plasma FAM3A and adiponectin levels in patients with varicosity with or without metabolic disease (MD; hyperlipidaemia, diabetes, and obesity), we observed a positive correlation between the levels of FAM3A and adiponectin." (PMID 41353211, 2025).
Obesity (2 papers, 2020 to 2025). Accumulation of substantial excess body fat. "In the present study, we identified FAM3A as a critical regulator for the treatment of IR under conditions of high lipid-induced obesity." (PMID 41353211, 2025). "We hope that targeting FAM3A will be beneficial for diagnosis and drug development to improve obesity-related IR in the future." (PMID 41353211, 2025). "Taken together, these findings suggest that increasing FAM3A expression in the body may represent a unique opportunity to avoid IR in individuals with obesity induced by high lipid levels." (PMID 41353211, 2025). "Another study found that under the condition of obesity, activation of the hepatic NFE2/miR-423-5p axis plays important roles in the progression of type 2 diabetes and NAFLD by repressing the FAM3A-ATP-Akt signaling pathway." (PMID 32351607, 2020).
steatosis (2 papers, 2022 to 2023). Increased lipid within the cytoplasm of cells. "Meanwhile, dulaglutide, an agonist of glucagon-like peptide-1 receptor (GLP-1A), promoted lipolysis and fatty acid oxidation by activating FAM3A to attenuate steatosis." (PMID 35800345, 2022).
type 2 diabetes (2 papers, 2017 to 2020). "Under obese condition, a decrease in FAM3A expression in adipose tissues plays important roles in the development of adipose dysfunction and type 2 diabetes." (PMID 28515350, 2017). "Under obese condition, a decrease in FAM3A expression in adipose tissue could contribute to the development of adipose dysfunction and type 2 diabetes." (PMID 28515350, 2017).
abdominal aortic aneurysm (1 paper, 2023). Enlargement and ballooning of the vessel that supplies arterial blood to the abdomen, pelvis and legs. "Similarly, overexpression of FAM3A in C57BL/6 mice attenuated elastase-induced abdominal aortic aneurysm." (PMID 37660071, 2023).
aneurysm (1 paper, 2023). Bulging or ballooning in an area of an artery secondary to arterial wall weakening. "The otherwise reduced expression level of the marker genes of contractile VSMCs (including Myocd, Srf, Myh11, Cnn1, Cnn2, and Tagln) in aneurysms was rescued in FAM3A-overexpressing aortas." (PMID 37660071, 2023). "Despite the higher mortality induced by AAA modeling in female mice than that in male mice, our results showed that the diameter of aneurysms was significantly reduced and the survival rate was increased in the mice supplemented with recombinant FAM3A compared to those in the matched control mice." (PMID 37660071, 2023). "In the in vivo study, we detected a gross lower expression level of CD68 and ARG1 (macrophage), Aggrecan (chondrocyte), OPN (osteoblast), ADIPQ (adipocytes), CD34 (mesenchymal cells), and LUM (fibroblasts) in the FAM3A-overexpressing aneurysm tissues compared with the matched Ad-sham tissues." (PMID 37660071, 2023). "Using RNA sequencing data from AngII-infused ApoE−/− aneurysm tissue, we identified 386 differentially expressed genes (DEGs) in FAM3A overexpression tissues compared to those of Ad-sham control tissues (|log2FC| > 1 and FDR < 0.05): 192 upregulated and 194 downregulated transcripts." (PMID 37660071, 2023).
aortic aneurysm (1 paper, 2023). A ruptured aneurysm located in the wall of the proximal portion of the descending aorta proceeding from the arch of the aorta. "To further evaluate the roles of FAM3A in the development of aortic aneurysms, we constructed murine AAA models using angiotensin II (AngII)-infused ApoE−/− mice and elastase-treated C57BL/6 mice." (PMID 37660071, 2023). "Despite these striking findings, the role of FAM3A in aortic aneurysms, particularly in terms of VSMC reprogramming, remains unknown." (PMID 37660071, 2023). "Furthermore, consistant with the findings in AAA patients, immunofluorescence staining, western blots, and qRT-PCR confirmed a lower expression level of FAM3A in murine aortic aneurysm tissues." (PMID 37660071, 2023). "In the current study, we unveiled important effects of this newly identified cytokine-like protein, FAM3A, on VSMC fate specification in aortic aneurysms." (PMID 37660071, 2023).
Cerebral ischemia (1 paper, 2023). Restriction of arterial blood supply to the brain associated with insufficient oxygenation to support the metabolic requirements of the tissue. "Our results are also in accordance with previous study demonstrating the protective role of the Snhg8/miR-384/Hoxa13/FAM3A axis in cerebral ischemia-induced neuronal apoptosis." (PMID 34853925, 2023).
cholangiocarcinoma (1 paper, 2021). A carcinoma that arises from the intrahepatic biliary tree (intrahepatic cholangiocarcinoma) or from the junction, or adjacent to the junction, of the right and left hepatic ducts (hilar cholangiocarcinoma). "Finally, six AS events, SLC38A10-44114-AT, IL18BP-17488-RI, NBPF10-5531-ES, THNSL2-54469-ME, FAM3A-90629-ES, and KIAA1432-85794-AT, were identified as independent risk factors for OS in cholangiocarcinoma." (PMID 34055632, 2021).
Cognitive impairment (1 paper, 2023). Abnormal cognition is characterized by deficits in thinking, reasoning, or remembering. "Overall, these results indicate that HI can elicit cognitive impairments as reflected by poor NSS, increased cerebral water content, and damaged neuronal cells, and that increased FAM3A expression may have rescuing effects." (PMID 34853925, 2023).
osteosarcoma (1 paper, 2022). A usually aggressive malignant bone-forming mesenchymal neoplasm, predominantly affecting adolescents and young adults. "miR-423-5p exhibited an inhibitory effect on osteosarcoma and ovarian cancer proliferation and was demonstrated to regulate FAM3A-ATP-Akt signaling in cultured hepatocytes." (PMID 35626751, 2022).
Sepsis (1 paper, 2025). Sepsis is defined as life-threatening organ dysfunction caused by a dysregulated host response to infection. "Ultimately, 8 key genes were identified: CD160, HELB, ING4, PIP5K1C, SRPRA (HR < 1); and CDCA7, FAM3A, PPP1R15A (HR > 1), and the hub genes showed apparent differences in expression between alive and dead sepsis patients." (PMID 40612938, 2025). "A lactylation-based prognostic model was developed, comprising eight key genes (CD160, HELB, ING4, PIP5K1C, SRPRA, CDCA7, FAM3A, PPP1R15A), and demonstrated strong predictive performance for sepsis outcomes (AUC = 0.78 in the training cohort; AUC = 0.73 in the validation cohort)." (PMID 40612938, 2025).
spinocerebellar ataxia (1 paper, 2023). "Two are in genes associated with spinocerebellar ataxia (ATXN3, ATXN7), while one is in FAM3A, encoding a cytokine-like protein that has been associated with modulation of PI3K signalling." (PMID 37974153, 2023).
viral infection (1 paper, 2017). "On Day 0, Day 4 and Day 8 post viral infection, Ad-FAM3A-transduced cells exhibited significantly higher FAM3A mRNA level when compared with Ad-GFP-treated cells." (PMID 28515350, 2017).
cancer (2 papers, 2023). A tumor composed of atypical neoplastic, often pleomorphic cells that invade other tissues. "In our study, FAM3A expression was negatively correlated with estimate score, stromal score and immune score in most cancer species, which meant that higher FAM3A expression was associated with lower TME content and higher tumor purity." (PMID 37704682, 2023). "From the heatmap of the log (fold change (FC)) of FAM3 family genes in 24 cancers, we can see that FAM3A and FAM3C showed a tendency to be highly expressed in the tumor tissues." (PMID 37704682, 2023). "FAM3A was negatively correlated with stromal score, immune score and estimate score in most of pan-cancer, which indicated that the higher expression of FAM3A, lower TME score, meant the higher content of tumor cells." (PMID 37704682, 2023). "The results of heatmap revealed that FAM3A and FAM3C were commonly highly expressed in pan-cancer tissues." (PMID 37704682, 2023). "FAM3A expression was positively correlated with FAM3D, and FAM3B expression in pan-cancer (Cor = 0.10, and 0.13)." (PMID 37704682, 2023). "As a cytokine-like gene, FAM3 family includes FAM3A, FAM3B, FAM3C, and FAM3D, and is involved in the occurrence and development of several cancers." (PMID 37056931, 2023).
metabolic disorders (2 papers, 2024 to 2025). "Taken together, these results suggest that FAM3A is a novel cytokine that is downregulated in metabolic disorders and can positively regulate adiponectin levels." (PMID 41353211, 2025). "We observed a positive correlation between FAM3A and adiponectin levels in patient plasma samples; although FAM3A increased intramyocellular lipid accumulation, it inhibited IR and metabolic disorders." (PMID 41353211, 2025). "Overall, the current findings have established FAM3A as a viable and exciting target for treating metabolic diseases." (PMID 38937853, 2024). "In the future, determining whether the increase in FAM3A levels in the body would be beneficial to the population with metabolic disorder, as delineated in the mouse models in our study, is worthy of investigation." (PMID 41353211, 2025). "Therefore, our study identified FAM3A/PPARα axis as a novel signaling pathway that regulates metabolic disorders and balances excess lipids and IR." (PMID 41353211, 2025). "Moreover, it should be noted that the disturbed cross-regulation loop between HSF1 and FAM3A pathways might play vital roles in the development of metabolic disorders." (PMID 38937853, 2024). "Interestingly, a positive linear regression relationship was observed between the plasma levels of FAM3A and adiponectin in patients with or without metabolic disease (MD)." (PMID 41353211, 2025).
tumor (1 paper, 2023). "The results demonstrated FAM3A was highly expressed in LICH tumor tissues compared to their normal counterparts, and high expression of FAM3A was significantly associated with poor prognosis in LICH patients." (PMID 37704682, 2023).
FAM3A also shares sentences with these, for which no sentence is quoted: fatty liver (1 paper); hyperlipidaemia (1); Hypertension (1); Impaired glucose tolerance (1); ovarian carcinoma (1); pancreatic cancer (1).